OR8K1 (olfactory receptor family 8 subfamily K member 1)
Description:
Odorant receptor.
Synonyms: OR11-182; OR8N1P
Tractability: Antibody: UniProt places it where antibodies can reach, with medium confidence; UniProt predicts a signal peptide or a membrane-spanning region; its Gene Ontology location is reachable by antibodies, with medium confidence.
Gene: Protein-coding gene on chromosome 11 (56,346,039 to 56,346,998, forward strand). Ensembl gene ENSG00000150261.
Subcellular location: Cell membrane
Pathways (Reactome):
Sensory Perception: Expression and translocation of olfactory receptors
Gene Ontology:
Molecular function: olfactory receptor activity; G protein-coupled receptor activity
Biological process: G protein-coupled receptor signaling pathway; sensory perception of smell; detection of chemical stimulus involved in sensory perception of smell
Cellular component: plasma membrane; membrane
Genetic constraint (gnomAD): Missense variants: 403 observed, 379.39 expected, observed/expected ratio (o/e) 1.06, 90% interval 0.98 to 1.15. Synonymous variants: 155 observed, 143.5 expected, observed/expected ratio (o/e) 1.08, 90% interval 0.95 to 1.23.
Homologues: Orthologues: chimpanzee OR8K1 (97% identical), macaque OR8K1 (96% identical), pig OR8K1 (86% identical), dog OR8K1 (84% identical), rabbit OR8K1 (83% identical), rat Or8k1 (81% identical), mouse Or8k1 (80% identical). Paralogues in human: OR8K3 (67% identical), OR8K5 (62% identical), OR8J2 (57% identical), OR8U1 (55% identical), OR8U3 (55% identical), OR8J1 (53% identical), OR8J3 (53% identical), OR5B12 (52% identical), OR8A1 (50% identical), OR5AR1 (50% identical), OR8D4 (50% identical), OR5J2 (49% identical), and 84 more.
Diseases named in the same sentence as OR8K1 in open-access papers:
OR8K1 is named in the same sentence as 1 disease in open-access papers, as found by Europe PMC text mining. Sharing a sentence is not in itself a finding about the gene and the disease.
OR8K1 shares sentences with these, for which no sentence is quoted: entropion (1 paper).